PTGFRN (prostaglandin F2 receptor inhibitor)
Diseases named in the same sentence as PTGFRN in open-access papers (continued):
Sharing a sentence is not in itself a finding about the gene and the disease.
cancer (13 papers, 2010 to 2025). A tumor composed of atypical neoplastic, often pleomorphic cells that invade other tissues. "We showed that PTGFRN expression was undetectable in non‐cancerous tissue samples and overexpressed in several patient‐derived cancer tissue samples." (PMID 40551322, 2025). "Conjugation of the fully human anti‐PTGFRN antibody 8C7 to the payload Duocarmycin using a cleavable valine‐citrulline linker resulted in an ADC that demonstrated high efficacy in inhibiting cancer cell proliferation in in vitro models." (PMID 40551322, 2025). "We have demonstrated a statistically significant and dose-dependent efficacy of the 33B7 ADC in inhibiting the proliferation of several cancer cell lines that express PTGFRN, when compared to control ADC antibody." (PMID 33503070, 2021). "Western blot analysis using an anti-PTGFRN antibody was used to examine PTGFRN expression in several cancer cell lines." (PMID 33503070, 2021). "In vitro treatment PTGFRN-positive cancer cell lines with the 33B7-saporin ADC inhibited their proliferation in a dose-dependent fashion." (PMID 33503070, 2021). "Our findings build on this emerging evidence and suggest that PTGFRN may serve as a pan‐cancer marker of EVs derived through non‐canonical, ESCRT‐independent pathways—distinct from the classical CD9‐, CD63‐, or CD81‐marked small EVs." (PMID 41039818, 2025). "This suggests that PTGFRN could be functioning through transmembrane receptor signaling that modulates pro-survival and promigratory signaling pathways in cancer." (PMID 35690717, 2022). "Using the selected mouse monoclonal antibody 33B7 to carry out immunoprecipitation, followed by mass spectrometry analysis, our laboratory has identified Prostaglandin F2 Receptor Negative Regulator (PTGFRN) as an internalizable cell-surface target expressed on several cancer cells." (PMID 33503070, 2021). "An interesting question that needs further exploration is the role of PTGFRN in cancer cells and whether its expression is correlated with aggressiveness." (PMID 33503070, 2021). "The studies presented here also provide the first evidence that internalization of PTGFRN can be coupled with payload delivery in cancer cells, and suggests that PTGFRN could be a novel therapeutic target for further ADC development." (PMID 33503070, 2021). "In this study, we detected a cancer-restricted gene fusion between PTGFRN and NOTCH2 in CRC." (PMID 22905095, 2012). "PTGFRN has been reported to be significantly overexpressed in several cancer types, making it an attractive target for ADC development as a cancer therapeutic." (PMID 40551322, 2025). "PTGFRN, also known as CD315, FPRP, CD9 partner-1, and EWI-F, is expressed in several types of cancer." (PMID 40047938, 2025). "The present paper describes the properties of this antibody 33B7, identifies its target as Prostaglandin F2 Receptor Negative Regulator (PTGFRN), and shows its efficacy as an ADC in several cancer cell lines." (PMID 33503070, 2021). "The remaining proteins are involved in the maintenance of the membrane structure (ACTG1 and PTGFRN), the uptake of EVs by endocytosis (CLTC), and the release of exosomes (PKM), in particular from cancer cells." (PMID 32886718, 2020). "Although various results were generated by deFuse and TopHat-Fusion, a fusion event between PTGFRN and NOTCH2 was the only cancer-specific fusion event identified by both algorithms." (PMID 22905095, 2012). "In our cancer sample, we detected that the first intron of PTGFRN is fused with the 3′ junction of the 17th exon of NOTCH2 to generate a chimeric PTGFRN-NOTCH2 transcript." (PMID 22905095, 2012). "We had shown previously that inhibition of PTGFRN expression in A431 cells and in DAOY cells inhibited cell proliferation in low serum, migration, clonogenicity, and Spheroid formation in 3D culture, all hallmarks of cancer aggressiveness." (PMID 40551322, 2025). "Unfortunately, in-depth research on PTGFRN as a cancer therapy target specifically is quite lacking." (PMID 33503070, 2021).
cancer (continued). "This makes PTGFRN a valuable target for ADC development, as it is preferentially expressed in certain cancers compared to non‐cancerous tissue, it can act as a biomarker to predict response and stratify patients, and is found to be overexpressed when certain cancers become metastatic." (PMID 40551322, 2025).
PTGFRN also shares sentences with these, for which no sentence is quoted: ovarian carcinoma (2 papers); adenocarcinoma (1); Alzheimer disease (1); biphasic mesothelioma (1); breast carcinoma (1); Clear Cell Carcinoma (1); dementia (1); gout (1); head and neck cancer (1); infection (1); kidney cancer (1); malaria (1); melanoma (1); mild cognitive impairment (1); myeloid leukemia (1); Pancreatic Duct Adenocarcinoma (1); papillary renal cell carcinoma (1); pericardial mesothelioma (1); pleural mesothelioma (1); prostate carcinoma (1); rheumatoid arthritis (1); small cell lung carcinoma (1); spindle cell carcinoma (1); thyroid cancer (1).